SNAP25 (synaptosome associated protein 25)
Diseases named in the same sentence as SNAP25 in open-access papers (continued):
Sharing a sentence is not in itself a finding about the gene and the disease.
agranulocytosis (1 paper, 2023). "In addition, clozapine-related weight gain was associated with LEP, SNAP-25 genes, and agranulocytosis risk with HLA-related polymorphisms." (PMID 36980961, 2023).
amnesia (1 paper, 2015). Pathologic partial or complete loss of the ability to recall past experiences ( AMNESIA, RETROGRADE) or to form new memories ( AMNESIA, ANTEROGRADE). "In our study, down-regulation of SNAP-25 suggest that amnesia, which was induced by post-training administration of morphine, may be partially due to decrease in neuronal excitability." (PMID 25901168, 2015).
atherosclerosis (1 paper, 2013). A disease characterized by the build-up of fatty material and calcium deposition in the arterial wall resulting in partial or complete occlusion of the arterial lumen. "Microarray data on the atherosclerosis-related down-regulation of nerve-specific genes were validated by immunoblot detection of the synaptosomal-associated 25 kDa protein (Snap25) as a neuronal synapse-specific protein." (PMID 23801967, 2013). "In contrast to captopril, vitamin E did not prevent the atherosclerosis-related decrease of the aortic Snap25 protein content." (PMID 23801967, 2013).
atrial fibrillation (1 paper, 2020). A disorder characterized by an electrocardiographic finding of a supraventricular arrhythmia characterized by the replacement of consistent P waves by rapid oscillations or fibrillatory waves that vary in size, shape and timing and are accompanied by an irregular ventricular response. "SNAP25, a proposed interaction partner of SYT10, is the target of botulinum toxin A. Injection of botulinum toxin A into the neural ganglia of CAD/atrial fibrillation patients was recently shown to reduce the occurrence of post-operational atrial fibrillation." (PMID 32678143, 2020).
deafness (1 paper, 2025). An inherited or acquired condition characterized by the complete loss of the ability to hear from one or both ears. "A previous study reported that the deletion of Snap25 in the inner hair cells induced deafness in mice as a result of reduced exocytosis, which was caused by degeneration of inner hair cells." (PMID 40553089, 2025).
delirium (1 paper, 2024). A disorder characterized by confusion; inattentiveness; disorientation; illusions; hallucinations; agitation; and in some instances autonomic nervous system overactivity. "Third, contrary to presumed role of synaptic dysfunction in delirium, SNAP-25 was only elevated in AD, but not in delirium." (PMID 38566855, 2024). "Median serum GFAP and CSF SNAP-25 levels were higher in the AD cohort than in non-AD controls, but not in the delirium cohort." (PMID 38566855, 2024). "Although SNAP-25 and NPTX2 did not exhibit significant differences in delirium, the exploration of synaptic biomarkers remains promising for enhancing our understanding of this condition." (PMID 38566855, 2024). "Subsequently, we analyzed whether a ratio of neurodegeneration to synaptic dysfunction (specifically, NFL compared to SNAP-25 or NPTX2 and tau compared to SNAP-25 or NPTX2) would more effectively differentiate patients with delirium from control groups (AD and non-AD)." (PMID 38566855, 2024).
endothelial dysfunction (1 paper, 2023). In vascular diseases, endothelial dysfunction is a systemic pathological state of the endothelium (the inner lining of blood vessels) and can be broadly defined as an imbalance between vasodilating and vasoconstricting substances produced by (or acting on) the endothelium. "For example, endothelial dysfunction is associated with reduced expression of several presynaptic (e.g., synaptosomal-associated protein-25 (SNAP-25) and growth associated protein-43 (GAP-43)) and postsynaptic (e.g., PSD95) proteins in human AD brains." (PMID 37238700, 2023).
episodic ataxia (1 paper, 2026). "This case broadens the genotypic and phenotypic spectrum of SNAP25-related DEE, highlighting febrile illness-triggered episodic ataxia as a previously unreported manifestation." (PMID 41769487, 2026).
gastric tumors (1 paper, 2025). "Dual immunofluorescence staining of 36 pairs of metastatic lymph nodes and paired primary gastric tumors revealed that PanCK+ SNAP25+ expression was higher in the metastatic lymph nodes than that in the primary tumors." (PMID 41203604, 2025).
glaucoma (1 paper, 2011). Increased pressure in the eyeball due to obstruction of the outflow of aqueous humor. "In the future, further in vitro and in vivo studies are required to show that optineurin causes glaucoma via regulating Bdnf, Ntf3, Snap25, and Nef1." (PMID 22194658, 2011).
Gliosis (1 paper, 2010). Gliosis is the focal proliferation of glial cells in the central nervous system. "This study found the frontal cortex to be the main region where intense oxidative stress phenomena (AOP-1) and synaptic protein expression (SNAP-25) were closely related to inflammatory cuffs, satellitosis and gliosis, which represent the most frequently observed neurological lesions." (PMID 20831786, 2010).
haemorrhoid (1 paper, 2020). "However, the results showed that the expression levels of all important node genes (CLTA, CLTC, RAB3A, SNAP25, SYT1, VAMP2) on Synaptic vesicle cycle pathways from haemorrhoid patient samples were lower significantly than them from healthy tissue samples." (PMID 32620169, 2020).
hearing loss (1 paper, 2024). "The lead-induced cochlear synaptopathy is associated with changes in the abundance of many synaptosomal proteins, and the increase in the abundance of proteins encoded by genes such as Snap25 and Vamp2 has been associated with hearing loss in other studies." (PMID 39104440, 2024).
Hepatic steatosis (1 paper, 2023). Steatosis is a term used to denote lipid accumulation within hepatocytes. "In addition to a reduction in the weight of all fat depots (epididymal WAT [eWAT], iWAT, retroperitoneal WAT [rpWAT], and iBAT), liver weight and hepatic steatosis were also reduced in Snap25Δ3/Δ3 mice compared with Snap25+/+mice." (PMID 37561580, 2023).
herpesvirus infections (1 paper, 2010). "However, the association of MMP-9 with AOP-1 and SNAP-25 expression related to BoHV-5 neurological cases has never been described in association with herpesvirus infections." (PMID 20831786, 2010).
Lambert-Eaton myasthenic syndrome (1 paper, 2023). Lambert-Eaton myasthenic syndrome (LEMS) is an autoimmune, presynaptic disorder of neuromuscular transmission characterized by fluctuating muscle weakness and autonomic dysfunction frequently associated with small-cell lung cancer (SCLC). "SYT2-CMS, SNAP25-CMS, VAMP1-CMS, UNC13A-CMS, RPH3A-CMS, and LAMA5-CMS are characterized by defects in the SNARE complex, and phenotypically similar to Lambert-Eaton myasthenic syndrome (LEMS)." (PMID 36835142, 2023).
lung fibrosis (1 paper, 2024). "We detected SNAP25 expression in the lung tissues of mice with BLM-induced lung fibrosis and TGF-β1-activated fibroblasts." (PMID 39523374, 2024). "In the current study, we examined the expression of STX11 and SNAP25 in the lung tissues from IPF patients and mice with BLM-induced pulmonary fibrosis as well as in the activated fibroblasts." (PMID 39523374, 2024). "Here, we showed that the expression levels of STX11 and SNAP25 were downregulated in the lung tissues from patients with IPF and mice with bleomycin (BLM)-induced lung fibrosis as well as in the activated fibroblasts." (PMID 39523374, 2024).
malignant pheochromocytomas (1 paper, 2013). "Given that, the BoT-induced SNAP25 cleavage results in a secretory blockade, BoT-EGF could be beneficial not only for palliative care prior to surgery but also as a long-duration pharmacological intervention of non-malignant pheochromocytomas." (PMID 23638840, 2013).
multiple sclerosis (1 paper, 2019). A progressive autoimmune disorder affecting the central nervous system resulting in demyelination. "Similarly, GC haplotype for rs3746544 of SNAP-25 gene and rs1051312 of SNAP-25 gene were associated with an increased risk for multiple sclerosis (p=0.022)." (PMID 30582321, 2019). "Similarly, Ddel polymorphism of SNAP-25 gene C/C genotype (p=0.059), syntaxin 1A T/C and C/C genotypes (p=0.005), and synaptotagmin XI gene C allele (p=0.001) were observed more frequently in patients with multiple sclerosis." (PMID 30582321, 2019).
myelomeningocele (1 paper, 2015). Myelomeningocele is the most severe form of spina bifida. "Nonetheless, investigators recently reported that a limited amount of SNAP-25 was cleaved by BoNT-A injection in patients with myelomeningocele." (PMID 26241848, 2015).
nasal polyps (1 paper, 2024). "In the incidence of eosinophils in nasal polyps, ILC2s are distributed near the SNAP-25 expression region, which indicated that there was a morphological coexistence relationship between SNAP-25 and ILC2s." (PMID 38956647, 2024).
neuroendocrine carcinoma (1 paper, 2024). A malignant neuroendocrine neoplasm composed of cells containing secretory granules that stain positive for NSE and chromogranin. "This study investigated the expression and role of Synaptosome associated protein 25 (SNAP25) in high-grade neuroendocrine carcinoma (HGNEC)." (PMID 39430761, 2024).
neuropathic pain (1 paper, 2025). Chronic pain caused by damage to nerve fibers. "Synaptosome‐associated protein 25 (SNAP25), a component of the SNARE complex, is a presynaptic plasma membrane protein involved in the regulation of neurotransmitter release and has been implicated in neuropathic pain and neuropsychiatric disorders." (PMID 39924344, 2025).
neurosarcoidosis (1 paper, 2022). A sarcoidosis that involves the nervous system. "The same 5 controls with high SNAP-25 levels were also exceeding the cutoff for high Ng levels (manually defined as >600 pg/ml), again with the highest levels observed in the subject with neurosarcoidosis (1457 pg/ml)." (PMID 35461266, 2022).
pancreatic tumor (1 paper, 2020). "Gene expression profiling from independent Gene Expression Omnibus (GEO) datasets confirms that REST mRNA levels are elevated in human pancreatic tumor samples and correspond with lower levels of REST target genes such as SNAP25, CHGA, and PDGB5." (PMID 32080178, 2020).
Photophobia (1 paper, 2023). Excessive sensitivity to light with the sensation of discomfort or pain in the eyes due to exposure to bright light. "By cleaving SNAP-25, BoNT-A inhibits synaptic exocytosis, blocking the neural transmission of these mediators and reducing pain and photophobia." (PMID 37404468, 2023). "Therefore, BoNT-A’s action at the neuromuscular junction results simultaneously in decreased muscle contraction and the increased cleavage of SNAP-25, which both reduce CGRP release, and together may explain the improved symptoms of pain and photophobia in our BoNT-A responders." (PMID 37404468, 2023).
Pleural effusion (1 paper, 2025). The presence of an excessive amount of fluid in the pleural cavity. "The SNAP25 variant c.593G > C (p.R198P), identified here in a fetal case with pleural effusion, lies within the SNARE domain, a region critical for synaptic vesicle fusion." (PMID 41401185, 2025). "While this variant’s association with neurodevelopmental phenotypes, our study reveals one novel observation, pleural effusion as a previously unreported feature, expanding the clinical spectrum of SNAP25-related disorders." (PMID 41401185, 2025).
progressive ataxia (1 paper, 2023). "Episodic Ataxia 2 is a rare disorder with an early onset characterized by progressive ataxia and one of the P/Q-channel mutations associated with EA2 is A454T, which was shown to have stronger inactivation coupled with a reduced modulation by Syntaxin 1A and SNAP-25, which reduced exocytosis." (PMID 37654674, 2023).
prostate (1 paper, 2022). "Due to our finding that the effect of SNAP25 protein on survival prognosis became more pronounced as the pathological grading of prostate patients became more advanced, the SNAP25 protein was validated as a prognostic biomarker and selected for further analysis." (PMID 35392903, 2022).
prostate tumor (1 paper, 2022). "This implies that high expression of SNAP25 may facilitate the migration of immune cells to prostate tumor tissue." (PMID 35392903, 2022). "Thus, SNAP25 may play a key role in the immune regulation of prostate tumors." (PMID 35392903, 2022).
psoriasis (1 paper, 2024). An autoimmune condition characterized by red, well-delineated plaques with silvery scales that are usually on the extensor surfaces and scalp. "This implies that, irrespective of the CGRP release mechanism (either SNAP25-dependent and -independent), the quantity of CGRP may be the major determinant for the pathogenesis of psoriasis." (PMID 38902277, 2024).
scrapie (1 paper, 2008). A fatal disease of the nervous system in sheep and goats, characterized by pruritus, debility, and locomotor incoordination. "We have previously shown SNAP25 to be down regulated in scrapie infected mice, potentially targeted by the up-regulated miR-128." (PMID 18987751, 2008).
sialorrhea (1 paper, 2025). "Since the 1990s, various clinical studies have confirmed the efficacy of injecting BTXA into the salivary glands to treat sialorrhea, a process that involves the cleavage of synaptosomal-associated protein 25 (SNAP-25) to inhibit acetylcholine release." (PMID 40940777, 2025).
temporal lobe epilepsy (1 paper, 2012). A localization-related (focal) form of epilepsy characterized by recurrent seizures that arise from foci within the temporal lobe, most commonly from its mesial aspect. "SNAP-25 is down-regulated in temporal lobe epilepsy animal models and in patients by proteomic analysis, which implies synaptosome dysfunction." (PMID 23028951, 2012).
trigeminal neuralgia (1 paper, 2021). Trigeminal neuralgia is a nerve disorder that causes a stabbing or electric-shock-like pain in parts of the face. "In a previous model of trigeminal neuralgia, subcutaneous BoNT/A was administered, and transient receptor potential (TRP) channels and SNAP-25 were analyzed to confirm the antinociceptive effect of BoNT/A associated with axonal transport." (PMID 34678997, 2021).
tumor (27 papers, 2008 to 2025). "Further investigations are warranted to elucidate the underlying mechanisms by which SNAP25 influences tumor growth and to explore the therapeutic applications of SNAP25 inhibitors in clinical settings." (PMID 39430761, 2024). "Clinically, high levels of neural synaptic transcripts (SYP and SNAP25) are associated with inferior prognosis and advanced tumor stage in pan-cancer TCGA tumors, indicating a tumor promoting role of TME neural signals." (PMID 37463926, 2023). "We used Gene Set Enrichment and Gene Ontology analyses to evaluate the function of SNAP25 and further explored the association between SNAP25 expression and tumor-infiltrating immune cells using the Tumor Immune Assessment Resource database." (PMID 35392903, 2022). "We further identified RUN domain containing 3A (RUNDC3A) as an upstream molecule that regulates SNAP25 expression, which is associated with tumor progression and chemoresistance in GNECs." (PMID 36182960, 2022). "Synaptosomal-associated protein 25 (SNAP25) was selected for analyzing its correlations with tumor-immune system in the TISIDB database." (PMID 33150073, 2020). "Cox proportional hazards regression analysis showed that SNAP25 was negatively associated with tumor risk." (PMID 32412599, 2020). "In addition, this paper reveals the significant correlations between SNAP25 and lymphocytes (NK, macrophage, mast cell, NKT), which indicates the potential association of tumor microenvironment and SNAP25." (PMID 33150073, 2020). "This potential mechanism involves the upregulation of synaptosomal-associated protein 25 (SNAP-25), which has been observed to increase GABA levels within the tumor microenvironment." (PMID 40900801, 2025). "The consistent tumor volume measurements further validate the effectiveness of SNAP25 suppression, highlighting its potential as a target for future cancer treatments." (PMID 39430761, 2024). "The substantial reduction in tumor volume observed in the experimental group compared to the control group indicates that SNAP25 plays a critical role in tumor proliferation and survival." (PMID 39430761, 2024). "Of these, we found that SNAP25 had the most important influence on tumor-infiltrating immune cells in PCa." (PMID 35392903, 2022). "From in vitro and in vivo studies, we observed that SNAP25 knockdown reduced GNEC cells proliferation and tumor growth, as well as increased susceptibility of GNEC cells to multiple chemotherapeutic agents 5-fluorouracil and paclitaxel." (PMID 36182960, 2022). "We also used gene ontology (GO) analysis, gene set enrichment analysis (GSEA), and several methods to explore the potential functions of the SNAP25 in tumor development and the immune microenvironment." (PMID 35392903, 2022). "Consistent with results using TCGA data, SNAP25 expression at the protein level was significantly lower in the tumor group than in the normal group." (PMID 35392903, 2022). "Compared with the control group in the GNEC xenograft model, we found that SNAP25 knockdown significantly reduced tumour cell growth in vivo." (PMID 35752613, 2022). "To gain more insight into the relationship between SNAP25 and the clinical presentation of PCa, we first analyzed its mRNA expression levels in tumor and normal prostate tissue samples." (PMID 35392903, 2022). "Collectively, our study demonstrated a novel mechanism in which overexpression of RUNDC3A and SNAP25 modulates Akt protein stability to enhance tumor growth and chemoresistance in GNEC." (PMID 36182960, 2022). "To verify these findings, we evaluated the relationship between SNAP25 expression and tumor-infiltrating immune cells derived from gene expression data using the MCPcounter R package to quantify the abundance of immune cells." (PMID 35392903, 2022).